DKK1 (dickkopf Wnt signaling pathway inhibitor 1)
Diseases named in the same sentence as DKK1 in open-access papers (continued):
Sharing a sentence is not in itself a finding about the gene and the disease.
tumor (continued). "A study on canine PCa demonstrated that alteration of Dkk-1 expression in a dog PCa cell line (Ace-1/DKK-1YFP-LUC) changed the metastatic phenotype and tumor growth in vivo." (PMID 34437475, 2021). "Positive DKK1 and FOXM1 staining were seen in 29/38 (76.3%) and 33/38 (86.8%) cases, respectively, while both proteins were minimally detected in the non-tumor regions of pancreatic ducts under our staining conditions." (PMID 34117362, 2021). "To validate the transcriptional cross-regulation of S100A4 and DKK1 in vivo, we analyzed the S100A4-regulated DKK1 expression in tumor tissue of xenograft mice after intrasplenic transplantation of HCT116 cells." (PMID 35008201, 2021). "Dickkopf-1(DKK-1), as a WNT signaling pathway inhibitor 1, was bound with RBM47 to inhibit the activation of the WNT pathway and exert a tumor suppressor effect." (PMID 34804951, 2021). "previously showed that DKK1-drived downregulation in β-catenin drives MDSC accumulation in the bone marrow, spleen, and at primary tumor sites, and controls their immune suppressive effects." (PMID 34093545, 2021). "The reduction of DKK1 activated the SGK3/FOXO3 pathway to accelerate cell migration and tumor metastasis." (PMID 33613114, 2021). "For the formal accuracy assessment following CLIA guidelines, DKK1 qPCR data was generated and compared to the manual H-score data for 20 G/GEJ tumor resections." (PMID 33972574, 2021). "Validation of the DKK1 RNAscope CISH assay was conducted to assess specificity, sensitivity, accuracy, and precision in G/GEJ tumor resections according to CLIA guidelines." (PMID 33972574, 2021). "Taken together, our findings in this study uncovered the tumor-suppressive roles of ZBTB38 to suppress cell proliferation and migration by upregulating DKK1 expression." (PMID 34697293, 2021). "Taken together these results indicate that the DKK1 RNAscope assay is specific, sensitive, accurate, and precise for staining of G/GEJ tumor tissue." (PMID 33972574, 2021). "Further, CKLF, DKK1 and MYC were identified as the 3 key OSCGs which also effectual in bulk RNA sequencing, and the nomogram consisting of these 3 OSCGs and tumor stage at diagnosis was constructed." (PMID 34828292, 2021). "Len-sh-circ_PVT1 promotedhe texpression of DKK1, NKD1, and p-GSK3β and inhibited wnt4 and β-catenin in tumor." (PMID 34336825, 2021). "Given that dickkopf-related protein 1 (DKK1) inhibits Wnt signaling through its direct binding to LRP5/6, DKK1 was initially considered a tumor suppressor in the β-catenin-dependent context." (PMID 33291655, 2020). "Hypermethylation in gene promoters is a general epigenetic modification in cancer formation, especially for inhibition of tumor-suppressive genes such as PCDH10, DKK1, and KLF4." (PMID 32701143, 2020). "Among them, DKK1, LDHA and MELTF are high-expressed in tumor tissues compared with tissue adjacent to carcinoma, but GNG7 is low-expressed." (PMID 33287749, 2020). "MiR-373-3p mimics reduced lncRNA-LET-induced up-regulation of DKK1 and TIMP2 levels, and attenuated lncRNA-LET-mediated anti-tumor effects in ccRCC cells." (PMID 31768131, 2019). "Therefore, DKK1 may enhance tumor growth via direct effect on cellular proliferation and/or indirectly through promoting tumoral angiogenesis or vasculogenic mimicry in the tumor microenvironment." (PMID 31649806, 2019). "The levels of AFP, TSGF, CEA, and DKK1 were much higher in the ConD+NDEA group than in the normal control group (p < 0.01); and Diet I and Diet II significantly inhibited the elevation of the serum tumor markers, AFP, TSGF, and DKK1 (p < 0.01)." (PMID 30680188, 2019). "Taken together, DKK1 appears to facilitate tumor invasion and migration through TGF- β1 by remodeling the tumor microenvironment and inducing inflammation." (PMID 31568519, 2019). "What’s more, tumor sphere formation assay showed siDKK1 increased tumor sphere formation ability of PTOV1-Sg2 cells, which proved that inhibiting DKK1 restored stemness of PTOV1-depleted cells." (PMID 31387622, 2019).
tumor (continued). "Interestingly, targeting DKK1 may also have important implications in the immunotherapy of MM patients, as active vaccination of murine MM models with DKK1-DNA vaccine was effective in preventing MM development and reducing tumor burden in mice with established MM85." (PMID 29330358, 2018). "Specially, it has been reported that CBX7 inhibited breast tumorigenicity through DKK-1-mediated suppression of the Wnt signaling pathway, suggesting that CBX7 was a critical tumor suppressor in human BC." (PMID 29190923, 2017). "A candidate‐based screen of tumor lysates and differential protein arrays of cultured HSC identified several established hepatotropic cytokines, including IGF2, RBP4, DKK1, and CCL5 as being negatively regulated by endosialin." (PMID 28373218, 2017). "Several factors related with the CSC phenotype, such as ALDH1A1, SOX2, DKK1 and NOTCH1, were increasingly upregulated in the emerging CSC subpopulations during tumor progression." (PMID 27292183, 2016). "Beside ALDH1A1 and SOX2, other molecules such as DKK1 and NOTCH1 were notably upregulated in CSCs during tumor progression." (PMID 27292183, 2016). "We were able to detect human DKK-1 in the blood of tumor-bearing mice and we found a correlation between DKK-1 level and tumor proliferation." (PMID 27049730, 2016). "The level of DKK1 expression in HCCA tissues was significantly correlated with metastasis to hepatic hilar lymph nodes (P=0.038) and tumor differentiation (P=0.039)." (PMID 27608843, 2016). "Consistently, in human HCCA tissues, DKK1 level was positively correlated with β-catenin and MMP-7 expression, as well as tumor hilar lymphatic metastasis." (PMID 27608843, 2016). "Following down-regulation of DKK1 expression, QBC939 and FRH0201 cells exhibited significantly diminished in vivo tumor formation compared with control cells." (PMID 27608843, 2016). "Recently, many tumor markers such as SCCA, CEA, CA19-9, MMP-9, IL-6, CYFRA 21–1, DKK-1, M-CSF, MiR-18a, MiR-1246 and many other genes were evaluated for ESCC diagnosis." (PMID 25608466, 2015). "Other proteins included adhesion receptors, such as ICAM-5 and selectin, tissue-remodeling factors, such as DKK-1 and MMP-2, and metabolic enzymes, such as adiponectin and insulysin, suggesting that EMMPRIN is a multifunctional regulator of tumor development." (PMID 26416452, 2015). "When DKK-1 activity was inhibited by either using neutralizing anti-DKK-1 antibodies or RNAi, an attenuation of the inhibitory effects of MSCs on tumor cell proliferation was observed." (PMID 26694366, 2015). "In conclusion, our data indicate that DKK1 and DKK2 regulate both tumor angiogenesis and perivascular coverage." (PMID 24091497, 2014). "Together, these data demonstrate that DKK1 negatively, and DKK2 positively, regulates tumor angiogenesis." (PMID 24091497, 2014). "Using an adenoviral infection and EC-specific transgenic mice, we show that DKK1 and DKK2 differentially regulate structure and functionality of tumor blood vessels, in addition to tumor angiogenesis." (PMID 24091497, 2014). "One of the most highly bound RBM47 mRNA targets, the secreted Wnt inhibitor DKK1, is stabilized by RBM47 and partially mediates RBM47 tumor suppressive function." (PMID 24898756, 2014). "DKK-1 level correlated significantly with TNM stage (P = 0.009), tumor grade (P = 0.02), lymph node metastasis (P = 0.001), and expression of HER2 (P = 0.002)." (PMID 25116444, 2014). "We studied DKK1 and DKK2 effects on tumor vessel functionality by injecting lectin into DKK Tg mice bearing B16F10 tumors and quantifying vessel staining, a surrogate of vascular perfusion, in subsequently harvested tumors." (PMID 24091497, 2014). "In the present study, we investigated the effects of DKK1 and DKK2 on tumor growth and angiogenesis." (PMID 24091497, 2014). "Taken together, our data indicate that DKK1 and DKK2 effects on tumor growth involve DKK-modulated angiogenesis and altered tumor neovascular structure." (PMID 24091497, 2014).
tumor (continued). "In conclusion, DKK1 and DKK2 regulate tumor vessel functionality, resulting in changes of tumor hypoxia status." (PMID 24091497, 2014). "Although these results demonstrate that DKK1 and DKK2 regulate growth of some tumor cell types, the effects of DKK1 and DKK2 on tumor angiogenesis has not been thoroughly studied." (PMID 24091497, 2014). "Collectively, these data demonstrate that DKK1 promotes HCC cell migration and invasion in vitro and tumor metastasis in vivo." (PMID 24325363, 2013). "Other previous work has demonstrated an inhibitory effect on tumor growth mediated by MSC secretion of the Wnt-inhibitor, Dkk-1, which decreases cell cycle gene expression via the Wnt/β-catenin pathway." (PMID 24040358, 2013). "Our studies also provide novel insights into roles for DKK1 in addition to canonical WNT signaling and the mechanism of CCIC tumor formation." (PMID 21317455, 2010). "The up-regulation of DKK2 consequently leads to a suppression of DKK1 and thus possibly contributes to EFT phenotype indirectly by interfering with the suppressive function of DKK1 on tumor growth." (PMID 19247449, 2009). "Of these, nine tumours displayed low ASCL1/high DKK1 and six tumours high ASCL1/low DKK1 expression." (PMID 19744316, 2009). "To date, four SFRP family genes (SFRP1, SFRP2, SFRP4 and SFRP5) and two DKK family genes (DKK1 and DKK3) have been identified as targets of epigenetic silencing in human tumours." (PMID 18283316, 2008). "Since Dkk-1 and RANKL inhibit osteogenic differentiation and activate osteoclasts, respectively, these proteins probably contribute to tumour expansion by inhibiting repair of the surrounding bone while simultaneously accelerating resorption." (PMID 17987039, 2007). "Inhibiting DKK1 could rejuvenate CD8+ T cell functionality, reorient the TIME towards an anti-tumor stance, and potentially augment the effectiveness of immunotherapies, including checkpoint inhibitors." (PMID 39788945, 2025). "Additionally, DKK1 can indirectly modulate the PI3K/AKT pathway by enhancing the activity of immunosuppressive M2 macrophages within the TME, thus contributing to tumor progression and immune evasion." (PMID 40686307, 2025). "Although DKK1 blocking did not reduce subcutaneous tumor growth, patients with high DKK1 expression exhibit poorer survival." (PMID 40025612, 2025). "The immunosuppressive characteristics of DKK1 play a significant role in shaping the tumor immune microenvironment by reducing the proliferation and functionality of cytotoxic CD8+ T cells, which are essential for effective anti-tumor responses." (PMID 39788945, 2025). "It is still unclear why bone and CAF-derived DKK1 do not compensate for each other, and that deletion of Dkk1 in one or the other compartment has such profound anti-tumor effects." (PMID 39885132, 2025). "While Dkk1 expression at the tumor site was not reduced compared to littermate controls, DKK1 levels in circulation were drastically reduced, indicating that bone-derived DKK1 contributes to systemic elevation of DKK1 during tumor progression." (PMID 39885132, 2025). "Intriguingly, αSMA-Dkk1cKO mice also showed a significant reduction in primary tumor growth compared to their littermate controls, despite displaying no changes in DKK1 levels in the bone and circulation but achieving efficient deletion in the tumor mass." (PMID 39885132, 2025). "Moreover, anti-DKK1 antibodies binding to DKK1 N-terminal CRD1 induced Wnt non-canonical JNK phosphorylation, immune cell activation, and tumor cell cytotoxicity." (PMID 40394415, 2025). "Surprisingly, we observe a strong nuclear DKK1 staining in the tumor cells, which is not typical for a secreted protein, although we cannot exclude that DKK1 has been secreted." (PMID 39885132, 2025). "While not directly supporting tumor proliferation, stromal-DKK1 suppresses NK cell activation and cytotoxicity by downregulating AKT/ERK/S6 phosphorylation." (PMID 39885132, 2025).
tumor (continued). "The role of DKK1 in fostering immunosuppression is partly facilitated through its interaction with CKAP4 on macrophages, activating the PI3K-Akt pathway and promoting an M2 phenotype that suppresses anti-tumor immunity." (PMID 39788945, 2025). "Based on these observations, we aimed to determine whether DKK1 directly affects NK cell cytotoxicity, and quantified NK cell-mediated killing of the cell trace violet (CTV)-labeled PyMT tumor cells by assessing the expression of 7-AAD via flow cytometry." (PMID 39885132, 2025). "In the KILR tumor cytotoxicity assays applied to SKBR3, NCI-N87, and Colo-205 tumor cells, bispecific antibody TB725-007 combining DKK1 CRD1 and CRD2 binders increased the cytotoxicity effect compared to that of DKK1 CRD2 binder SC52-002 alone." (PMID 40394415, 2025). "In breast carcinoma, the LRP5Δ receptor (internally truncated LRP5 receptor) is expressed at all disease stages and is involved in tumor cell proliferation and growth through Wnt3-mediated β-catenin-driven transcription activation without DKK-1." (PMID 40940800, 2025). "Our work positions DKK1 as a negative modulator of anti-tumor immunity via suppression of NK cell cytotoxicity and raises the importance of DKK1 targeting to improve NK cell-directed therapies." (PMID 39885132, 2025). "Additionally, DKK1 directly impedes T cell receptor signaling, reducing CD8+ T cell responsiveness to tumor antigens and contributing to resistance against therapies like anti-PD-1 checkpoint blockade in CRC." (PMID 39788945, 2025). "The correlation between CKAP4 expression in tumor cells and poor RFS with advanced clinicopathological characteristics in the present study may represent the interaction of CKAP4 and DKK1." (PMID 40282454, 2025). "In nodular fasciitis, chromosomal translocations cause overexpression of USP6, which activates the Wnt/β-catenin pathway.To further determine the role of Wnt signaling in USP6-mediated tumor growth, they tested USP6/NIH 3T3 cells with DKK1, a secreted protein that inhibits Fzd receptor activation." (PMID 40348771, 2025). "It has been shown that the inhibitor of the DKK1 pathway can suppress WNT3A-dependent OPG expression in osteoblasts, impairing osteogenesis, and artificial stimulation of WNT3A in MM can enhance osteogenesis and reduce tumor growth." (PMID 40650009, 2025). "Cancer cell-derived DKK1 contributes to tumor progression by mediating interactions between cancer cells and fibroblasts within the tumor, rather than directly affecting the cancer cells." (PMID 40025612, 2025). "Targeting TFF1, PPA1, DKK1, LGR6, and MARCH1—while considering the tumor-suppressive role of TET1—may offer novel therapeutic avenues to overcome chemoresistance and improve patient outcomes." (PMID 40862711, 2025). "We found increased expression of Dkk1 in crushed bones devoid of marrow cells of tumor bearing mice compared to no tumor controls." (PMID 38659818, 2024). "DKK1 does not support tumor proliferation directly but rather suppresses the activation and tumoricidal activity of NK cells." (PMID 38659818, 2024). "Bone cells contribute to the elevated levels of circulating DKK1 in response to a distant tumor, while CAFs produce DKK1 at tumor site and do not affect DKK1 levels systemically." (PMID 38659818, 2024). "In the DKK1-stained subgroup, our scoring method showed that 71% of samples with DKK1-positive tumor cells had no clinicopathological relevance." (PMID 39630300, 2024). "DKK1 predominantly manifested expression in tumor cells as opposed to normal epithelial cells and immune/stromal cells, aligning with our findings from single-cell analysis." (PMID 39505867, 2024). "Next, we investigated DKK1 expression in the PyMT, 4T1, and EO771 tumor models." (PMID 38659818, 2024).
tumor (continued). "While Dkk1 expression at tumor site was not reduced compared to littermate controls, DKK1 levels in circulation were drastically reduced, indicating that bone-derived DKK1 contributes to systemic elevation of DKK1 during tumor progression." (PMID 38659818, 2024). "In addition, DKK1 mRNA expression levels were significantly related to the cancer stage, HPV status, nodal-metastasis status, and tumor grade of individuals with HNSCC." (PMID 38376441, 2024). "Intriguingly, aSMA-Dkk1cKO also showed to a significant reduction in primary tumor growth compared to littermate controls, despite showing efficient deletion of Dkk1 only in the tumor mass but no changes in the bone and circulation." (PMID 38659818, 2024). "DKK1 was highly expressed in HSNCC patients and could promote tumor progression in vitro and in vivo." (PMID 38525111, 2024). "Dickkopf-related protein 1 (DKK-1), which is secreted by CAFs, is an inhibitor of Wnt signaling, and its expression has been reported to be a prognostic factor in the prediction of tumor recurrence and survival in patients with advanced GC." (PMID 37173977, 2023). "Tumour‐specific overexpression of DKK1 was achieved by co‐injecting a plasmid expressing both HA‐tagged DKK1 and RFP 35 and allows us to lineage trace DKK1 overexpressing cells." (PMID 35924447, 2023). "Similarly, our data showed that when DKK1 was inhibited by the small molecule, WAY-262611, the anti-tumor efficacy of SOR on cell viability, invasion, migration, and colony formation was significantly enhanced in HCC cells." (PMID 38012711, 2023). "The binding DKK1 and CKAP4 can trigger downstream signaling pathways, including PI3K/AKT and MAPK1/3, thereby influencing cellular functions and promoting the proliferation, migration, and invasion of tumor cells." (PMID 37835450, 2023). "The incremental process of bone metastasis development is initiated by establishing a premetastatic niche at distant organs created by several tumor-derived factors (CCL2, IL6, lysyl oxidase (LOX), and Dickkopf WNT signaling pathway inhibitor 1 (DKK1)) of the primary tumor." (PMID 37296869, 2023). "Despite higher expression of Cxcl2, we saw no increase in tumour neutrophil recruitment (determined by percentage of Myeloperoxidase‐positive cells) when DKK1 was overexpressed in Nicd/Akt or KrasG12D/gTrp53 tumours." (PMID 35924447, 2023). "Our results showed higher expression of Dkk1 in tumours with nuclear β-catenin expression, suggesting negative feedback loop between Wnt signalling and Wnt antagonists, as has been proposed by previous studies." (PMID 36969079, 2023). "Excessive DKK1 production could indirectly establish a tumor niche, resulting in AML progression, while suppression of DKK1 by exogenous agents delayed AML progression and prolonged survival in animal models." (PMID 36661526, 2023). "Although the authors did show reduced DKK-1 concentrations in combination-treated mice with breast cancer, parameters to show the global suppression of tumors, such as tumor weight and volume, were not recorded." (PMID 36579200, 2022). "Furthermore, DKK1 and CKAP4 were found in tumor lesions in more than 70% of lung squamous cell carcinoma patients." (PMID 35355709, 2022). "Whilst our findings now need to be replicated in larger cohorts, our data suggest adjunct markers such as DKK1 and BCMA may be used in conjunction to track tumour burden, depth of response and early relapse." (PMID 36612090, 2022). "Pulmonary seeding of tumor cells was shown not to be affected by DKK1 depletion as examined by bioluminescent imaging 4 h after cell injection." (PMID 35296660, 2022). "Based on TCGA-LUAD transcriptome data, differential expression analysis showed that with the comparison of normal samples, DKK1 and LOXL2 expression were significantly increased in tumor tissues, whereas MGP and SLIT3 were markedly overexpressed in non-tumoral tissues." (PMID 36185284, 2022).